HAPLN3 (hyaluronan and proteoglycan link protein 3)
Description:
May function in hyaluronic acid binding.
Synonyms: EXLD1; HsT19883
Tractability: Antibody: UniProt places it where antibodies can reach, with medium confidence; UniProt predicts a signal peptide or a membrane-spanning region; its Gene Ontology location is reachable by antibodies, with medium confidence; the Human Protein Atlas places it where antibodies can reach.
Gene: Protein-coding gene on chromosome 15 (88,877,294 to 88,895,597, reverse strand). Ensembl gene ENSG00000140511.
Subcellular location: Secreted, extracellular space, extracellular matrix
Subcellular location (Human Protein Atlas): Cytosol; Plasma membrane; Predicted to be secreted
Gene Ontology:
Molecular function: hyaluronic acid binding
Biological process: central nervous system development; skeletal system development; cell adhesion
Cellular component: extracellular region; gel phase of interstitial matrix; perineuronal net; synapse
Genetic constraint (gnomAD): Loss-of-function variants: 30 observed, 31.69 expected, observed/expected ratio (o/e) 0.95, 90% interval 0.71 to 1.28. The upper end of that interval is the gene's LOEUF score, 1.28, which puts it in group 5 of 6, group 1 being the genes least tolerant of losing a copy. Missense variants: 513 observed, 521.16 expected, observed/expected ratio (o/e) 0.98, 90% interval 0.92 to 1.06. Synonymous variants: 211 observed, 221.07 expected, observed/expected ratio (o/e) 0.95, 90% interval 0.85 to 1.07.
Homologues: Orthologues: chimpanzee HAPLN3 (99% identical), macaque HAPLN3 (97% identical), pig HAPLN3 (82% identical), mouse Hapln3 (81% identical), guinea pig HAPLN3 (80% identical), rat Hapln3 (79% identical), tropical clawed frog hapln3 (66% identical), zebrafish hapln3 (56% identical). Paralogues in human: HAPLN1 (51% identical), HAPLN4 (47% identical), HAPLN2 (45% identical), BCAN (41% identical), NCAN (39% identical), ACAN (38% identical), VCAN (38% identical).
Diseases named in the same sentence as HAPLN3 in open-access papers:
HAPLN3 is named in the same sentence as 17 diseases in open-access papers, as found by Europe PMC text mining. Sharing a sentence is not in itself a finding about the gene and the disease. The quoted sentences say what the papers report.
breast carcinoma (6 papers, 2019 to 2024). "Apart from HAPLN1, clinical data analysis showed that HAPLN3 overexpression was related to breast cancer metastasis and its level was closely related to the depth of tumour invasion, lymph node invasion and distant metastases in ccRCC." (PMID 38791985, 2024). "Meanwhile, overmodulated expression of HAPLN3 was suggested to relate with the initiation of breast cancer." (PMID 36818162, 2023). "Meanwhile, over-modulated expression of HAPLN3 was suggested to relate with the initiation of breast cancer; however, its function in melanoma is presently unclear." (PMID 33868993, 2021). "Increased expression of HAPLN3 has been reported in breast cancer while TSG-6 has been found to be increased in colon cancer, ovarian cancer, bladder cancer, and prostate cancer In colon and ovarian cancer, higher TSG-6 levels were correlated with poor prognosis." (PMID 38791985, 2024). "The expression of HAPLN3 gene has significantly increased in the tissue of breast cancer compared to normal breast tissue, which indicates that up-expression of HAPLN3 could contribute to the development of breast cancer." (PMID 35798030, 2022). "Besides, the expression of HAPLN3 was shown to be significantly higher in breast cancer tissues compared to the normal breast tissues." (PMID 34211850, 2021). "HAPLN3 and MFG-E8 genes are closely related to the occurrence of breast cancer, which indicates that they are likely important to the development of mammary gland." (PMID 35798030, 2022). "HAPLN3 and BRF1 have been found relevant to breast cancer in the literature and they are both found to be among the most effective genes for our classification system." (PMID 31195961, 2019).
prostate carcinoma (6 papers, 2017 to 2024). A carcinoma that arises from epithelial cells of the prostate gland. "As for HAPLN3, it has been identified as a novel diagnostic and prognostic biomarker for prostate cancer." (PMID 34211850, 2021). "ctDNA analysis based on methylation of three of these genes (ST6GALNAC3, CCDC181, and HAPLN3) could detect prostate cancer with 100% diagnostic specificity and 67% diagnostic sensitivity." (PMID 33942482, 2021). "Combined with the signature of other genes, HAPLN3 methylation has been used as a biomarker to predict prostate cancer recurrence." (PMID 38791985, 2024). "In the same study, using ddPCR, promoter methylation of these two genes (ST6GALNAC3 and ZNF660) and additionally CCDC181 and HAPLN3 was evaluated in ctDNA of 27 patients with prostate cancer and 10 patients with benign prostate hyperplasia using MS‐ddPCR." (PMID 33942482, 2021). "The mentioned studies analyzed prostate cancer tissues; however, the HAPLN3 DNA methylation from prostate cancer patients’ circulating tumor DNA was also shown to be a part of the three methylated gene signature with potential role in prostate cancer diagnosis and risk stratification." (PMID 38255186, 2023). "Namely, the gene encoding HAPLN3 (hyaluronan and proteoglycan link protein 3) ECM proteoglycan was found to be a part of the three-gene DNA methylation biomarker with diagnostic and prognostic potential in prostate cancer." (PMID 38255186, 2023). "In localized and de novo metastatic prostate cancer, three genes, DOCK2, HAPLN3, and FBXO30, were found to be specifically hypermethylated in prostate cancer tissues using MS‐ddPCR." (PMID 33942482, 2021). "In this study, we show that prostate cancer-specific hypermethylation of the eight genes AOX1, CCDC181 (C1orf114), GABRE, GAS6, HAPLN3, KLF8, MOB3B, and SLC18A2 can be detected by qMSP with very high sensitivity and specificity in scarce prostate needle biopsy samples taken at the time of diagnosis." (PMID 28084441, 2017).
melanoma (5 papers, 2020 to 2023). A malignant, usually aggressive tumor composed of atypical, neoplastic melanocytes. "Three genes, i.e., CLEC7A, CLEC10A, and HAPLN3 have been reported to exhibit prognostic significance with respect to melanoma for the first time, while HCP5 has been reported to inhibit the development of cutaneous melanoma." (PMID 33868993, 2021). "However, four genes, i.e., HPDL, GRIPAP1, GBP2, and TRIM34, have been reported to exhibit prognostic significance with respect to melanoma for the first time, while HAPLN3, CCL8, FCGR2A, and IFITM1 have been reported to relate with the initiation and immune microenvironment of cutaneous melanoma." (PMID 36818162, 2023). "In this study, 7 genes (CYTL1, CCL8, FCGR2C, OAS1, HAPLN3, WIPF1, CLIC2) were identified as prognostic signatures for melanoma." (PMID 33428606, 2021). "The four genes (CLEC7A, CLEC10A, HAPLN3, and HCP5) were also identified as meaningful anti-tumoral genes in melanoma." (PMID 33868993, 2021). "By analyzing the TCGA genomics data of SEL1L3, HAPLN3, BST2, and IFITM1, we found that the gene alteration rates in melanoma were 10% for SEL1L3, 4% for HAPLN3, 0.8% for BST2, and 0.6% for IFITM1, and these alterations were not recurrent." (PMID 33753855, 2021). "The genes in this signature, SEL1L3, HAPLN3, BST2, and IFITM1, may be functionally involved in melanoma progression and immune response." (PMID 33753855, 2021). "Among these, CLEC7A, CLEC10A, and HAPLN3 have not yet been reported to be correlated with melanoma before." (PMID 33868993, 2021).
cutaneous melanoma (3 papers, 2021 to 2024). A primary melanoma arising from atypical melanocytes in the skin. "HAPLN3 has been proposed as a marker to predict survival and optimise the treatment of cutaneous melanoma." (PMID 38791985, 2024). "Several pyroptosis-associated genes including HAPLN3 were highly associated with immune infiltration, immune checkpoints, treatment responses, immunoinflammatory response which have been used to evaluate immunity in the TME of cutaneous melanoma." (PMID 38791985, 2024).
clear cell renal cell carcinoma (1 paper, 2024). "HAPLN3 acts as an oncogenic factor in cells, and a loss of HAPLN3 hinders the ability of clear cell renal cell carcinoma (ccRCC) cells to proliferate, migrate, and invade by suppressing activation of ERK1/2." (PMID 38791985, 2024).
diabetes (1 paper, 2020). "Furthermore, HAPLN3 (Hyaluronan and proteoglycan link protein 3) has previously been associated with diabetes in epidemiological studies." (PMID 32764569, 2020).
glioma (1 paper, 2024). A benign or malignant brain and spinal cord tumor that arises from glial cells (astrocytes, oligodendrocytes, ependymal cells). "While mutations in EFEMP2, ADAM10, SERPINH1, ADAM15, GAS6 and TNXB were detected only in patients with glioma grade 3, mutations in LTBP2, DCN, CRELD1 and HAPLN3 were observed only in patients with glioma grade 4, GBM." (PMID 38272115, 2024).
Hereditary breast cancer (1 paper, 2019). Breast carcinoma that has developed in relatives of patients with history of breast carcinoma. "Among the highest-scoring genes detected using the proposed method, it is suspected that STARD3, PGAP3, ORMDL3, PSMD3 and HAPLN3 are the biomarkers of the HER2 + subtype, thus indicating that FOXC1 can identify basal-like subtypes in hereditary breast cancer cohorts." (PMID 31296201, 2019).
Obesity (1 paper, 2020). Accumulation of substantial excess body fat. "Obesity group showed a higher mutation frequency of LDHAL6B, CPXM2, HAPLN3, and so on." (PMID 33197880, 2020).
renal carcinoma (1 paper, 2022). A carcinoma arising from the epithelium of the renal parenchyma or the renal pelvis. "NNMT, PLOD2, HAPLN3, PLIN2, and SLC16A3 showed medium to strong tumor-specific staining in more than 90% renal cancer samples, indicating higher general applicability of these biomarkers." (PMID 35440542, 2022).
tumor (9 papers, 2018 to 2024). "DNA epigenetic analysis showed HAPLN3-methylated circulating tumour DNA(ctDNA) was widely found in de novo metastatic PCa (mPCa) and was markedly elevated in high-volume mPCa." (PMID 38791985, 2024). "HAPLN3 has been reported to play an important role in maintaining the stability of the extracellular matrix, thereby regulating the mobility and migration of tumor cells." (PMID 34335689, 2021). "LGALS1, B4GALT6, and GALNT11 were upregulated and MGAT5, MAN1A1, MANBA, LUM, GALNT1 and 7, HAPLN3, and ST6GALNAC5 were downregulated in Fra-2 cl 1 select primary tumours, while MGAT4A was upregulated." (PMID 34693476, 2022). "Specificity/sensitivity for high tumor volume was 81%/71% for DOCK2, 71%/89% for HAPLN3, and 75%/77% for FBXO30." (PMID 32486483, 2020). "In de novo mPCa patients, we detected methylated ctDNA in 32.3% of the patients with low tumor volume and in 89.3% of patients with high tumor volume using the DOCK2, HAPLN3, and FBXO30 assays (positive for at least one assay)." (PMID 32486483, 2020). "In contrast, methylated ctDNA was detected in 89.2% (25/28) of mPCa patients with high tumor volume; 20/28 (71.4%) patients positive for DOCK2, 25/28 (89.2%) positive for HAPLN3, and 13/17 (76.5%) positive for FBXO30." (PMID 32486483, 2020). "In mPCa patients with low tumor volume, methylated ctDNA was detected in a total of 32.3% (10/31) of the patients, with 6/31 (19.4%) patients positive for DOCK2, 9/31 (29.0%) positive for HAPLN3, and 3/12 (25.0%) positive for FBXO30." (PMID 32486483, 2020). "Moreover, as proof of principle, we successfully detected highly PC‐specific hypermethylated circulating tumor DNA (ctDNA) for ST6GALNAC3,ZNF660,HAPLN3, and CCDC181 in liquid biopsies (serum) from 27 patients with PC vs. 10 patients with BPH, using droplet digital methylation‐specific PCR analysis." (PMID 29465788, 2018).
cancer (5 papers, 2017 to 2021). A tumor composed of atypical neoplastic, often pleomorphic cells that invade other tissues. "The physiological role of HAPLN3 (hyaluronan and proteoglycan link protein 3) is less clear, although it has been linked to height (UK Biobank data) and cancer." (PMID 32625236, 2020). "However, there is a need for further research to understand the function of FCGR2C and HAPLN3 in cancer." (PMID 33428606, 2021).
infection (1 paper, 2024). The state of being infected such as from the introduction of a foreign agent such as serum, vaccine, antigenic substance or organism. "HAPLN3 is involved in ERK signaling and ECM regulation, two important biological pathways altered during infection." (PMID 37918965, 2024).
HAPLN3 also shares sentences with these, for which no sentence is quoted: Alzheimer disease (1 paper); benign prostatic hyperplasia (1); ovarian carcinoma (1); triple-negative breast carcinoma (1).